SLC6A12 (solute carrier family 6 member 12)
Description:
Transporter that mediates cellular uptake of betaine and GABA in a sodium- and chloride-dependent process. May have a role in regulation of GABAergic transmission in the brain through the reuptake of GABA into presynaptic terminals, as well as in osmotic regulation. Probably also involved in renal and hepatic osmotic regulation (By similarity).
Synonyms: BGT1; BGT-1; GAT2
Tractability: Small molecule: a high-quality ligand is known; it belongs to a druggable protein family. Antibody: its Gene Ontology location is reachable by antibodies, with high confidence; UniProt places it where antibodies can reach, with medium confidence; UniProt predicts a signal peptide or a membrane-spanning region. PROTAC: ubiquitination databases record sites on it; its protein half-life has been measured; a small molecule that binds it is known.
Target class: SLC superfamily of solute carriers; SLC06 neurotransmitter transporter family; Electrochemical transporter; Transporter
Safety:
Unwanted effects reported when the protein is acted on. In parentheses: how it was acted on, where the effect was seen, and who reports it.
aspirin-intolerant asthma (source: ClinPGx)
Gene: Protein-coding gene on chromosome 12 (190,069 to 220,144, reverse strand). Ensembl gene ENSG00000111181.
Subcellular location: Basolateral cell membrane; Cell membrane
Subcellular location (Human Protein Atlas): Vesicles
Pathways (Reactome):
Metabolism: Creatine metabolism
Neuronal System: Reuptake of GABA
Transport of small molecules: Amino acid transport across the plasma membrane
Gene Ontology:
Molecular function: gamma-aminobutyric acid:sodium:chloride symporter activity; monocarboxylic acid transmembrane transporter activity; protein binding; amino acid transmembrane transporter activity; glycine betaine:sodium:chloride symporter activity; transmembrane transporter activity
Biological process: gamma-aminobutyric acid transport; monocarboxylic acid transport; amino acid transport; gamma-aminobutyric acid reuptake; glycine betaine transport; sodium ion transmembrane transport; amino acid transmembrane transport; neurotransmitter transport
Cellular component: basolateral plasma membrane; membrane; plasma membrane; presynapse
Genetic constraint (gnomAD): Loss-of-function variants: 42 observed, 62.77 expected, observed/expected ratio (o/e) 0.67, 90% interval 0.52 to 0.87. The upper end of that interval is the gene's LOEUF score, 0.87, which puts it in group 3 of 6, group 1 being the genes least tolerant of losing a copy. Missense variants: 618 observed, 739.98 expected, observed/expected ratio (o/e) 0.84, 90% interval 0.78 to 0.89. Synonymous variants: 301 observed, 298.64 expected, observed/expected ratio (o/e) 1.01, 90% interval 0.92 to 1.11.
Homologues: Orthologues: chimpanzee SLC6A12 (99% identical), macaque SLC6A12 (95% identical), dog SLC6A12 (91% identical), mouse Slc6a12 (88% identical), rat Slc6a12 (87% identical), guinea pig SLC6A12 (86% identical), pig SLC6A12 (84% identical), tropical clawed frog slc6a13 (71% identical). Paralogues in human: SLC6A13 (69% identical), SLC6A11 (65% identical), SLC6A6 (59% identical), SLC6A8 (52% identical), SLC6A5 (43% identical), SLC6A7 (43% identical), SLC6A9 (42% identical), SLC6A3 (41% identical), SLC6A2 (41% identical), SLC6A4 (40% identical), SLC6A14 (39% identical), and 6 more.
Diseases named in the same sentence as SLC6A12 in open-access papers:
SLC6A12 is named in the same sentence as 27 diseases in open-access papers, as found by Europe PMC text mining. Sharing a sentence is not in itself a finding about the gene and the disease. The quoted sentences say what the papers report.
epilepsy (6 papers, 2012 to 2025). A brain disorder characterized by episodes of abnormally increased neuronal discharge resulting in transient episodes of sensory or motor neurological dysfunction, or psychic dysfunction. "KDM5C gene silencing leads to down-regulation of SCN2A, CACNA1B; CACNA1H; SCL4A3, SLC18A1, and SLC6A12, All of these KDM5C target genes have been linked to neurological disorders such as epilepsy, autism or schizophrenia." (PMID 39948613, 2025). "It implies a possible role of SLC6A12 in drug resistance epilepsy as many of the drugs for the treatment of seizures target GABA transporters." (PMID 26076492, 2015).
schizophrenia (5 papers, 2016 to 2025). A major psychotic disorder characterized by abnormalities in the perception or expression of reality. "Interestingly, glioblastoma, gastric cancer, and colorectal cancer, which are dominant in males, are associated with ADGRB1, and schizophrenia and autism, which are also dominant in males, are associated with SLC6A12." (PMID 27561550, 2016). "Of particular interest are the SLC6A12 gene coding for a GABA transporter previously associated with negative symptoms in schizophrenia and the insulin receptor substrate 2 which has been proposed to regulate dopamine cell morphology." (PMID 35105872, 2022).
ovarian carcinoma (4 papers, 2020 to 2025). A malignant neoplasm originating from the surface ovarian epithelium. "High expression of the SLC6A12 gene in ovarian cancer is associated with a poorer prognosis, specifically for serous-type ovarian cancer." (PMID 41465326, 2025). "Consistently, SLC6A12 shows upregulated expression in metastatic sites of ovarian cancer and has been proven to promote the invasion and migration of ovarian cancer cells in vitro." (PMID 32647070, 2020). "SLC6A12 is a key gene that promotes aggressive metastasis during ovarian cancer progression." (PMID 36875704, 2023). "SLC6A12 were found to be highly expressed in ovarian cancer." (PMID 32647070, 2020). "A large number of putative suppressor genes that are silenced or activated by aberrant methylation have been identified in ovarian cancer, including hypermethylation of OPCML, RASSF1, CDKN2B as well as classical tumor suppressors BRCA1, p16 and MLH1, and hypomethylation of LINE-1, SLC6A12 and PRAME." (PMID 35710397, 2022).
diabetes (1 paper, 2021). "Of note, a missense mutation inducing a pre-mature stop codon in the SLC6A12 gene increases the odds ratio for T2D 15.8 times (dbSNP: rs199521597), establishing its key role in limiting the incidence of diabetes." (PMID 34192533, 2021).
muscular dystrophy (1 paper, 2018). Muscular dystrophy (MD) refers to a group of more than 30 genetic diseases characterized by progressive weakness and degeneration of the skeletal muscles that control movement. "In comparison, only a small minority of tissue-infiltrating CD68+ cells in DM and in muscular dystrophy tissues were SLC6A12 positive, and the more sparse inflammatory cells observed in IMNM tissues were SLC6A12 negative." (PMID 30364257, 2018). "In tissues from muscular dystrophy patients, the SLC6A12 muscle fiber staining pattern was similar to inflammatory myopathies, with diffuse staining mostly in small regenerating CD56 positive muscle fibers and discontinuous sarcolemmal staining in subsets of CD56 negative muscle fibers." (PMID 30364257, 2018).
type 2 diabetes (1 paper, 2021). "Missense mutations in the SLC6A12 and SLC6A13 genes are significantly associated with an increased incidence of type 2 diabetes (T2D)." (PMID 34192533, 2021). "We used the Accelerating Medicines Partnership Type 2 Diabetes Knowledge Portal to understand the effect of missense mutations in genes encoding the hepatic GABA transporters (SLC6A6, SLC6A8, SLC6A12, and SLC6A13)." (PMID 34192533, 2021).
inflammatory myopathies (1 paper, 2018). "The trimethylglycine betaine appears also important for proper muscle functioning, although SLC6A12 knockout mice have been reported to develop only mild myopathy." (PMID 30364257, 2018). "SLC5A3 and SLC6A12 were expressed by inflammatory cells in inflammatory myopathy muscle biopsies." (PMID 30364257, 2018).
SLC6A12 also shares sentences with these, for which no sentence is quoted: tumor (4 papers); autism (3); astrocytoma (2); neurodegenerative disease (2); age (1); amyotrophic lateral sclerosis (1); cancer (1); cognitive deficits (1); colorectal cancer (1); epileptic seizures (1); gastric cancer (1); glioblastoma (1); infection (1); Intellectual disability (1); neurological disorders (1); Obesity (1); Parkinson disease (1); rheumatoid arthritis (1); Stroke (1); virus infection (1).